SIRT3 (sirtuin 3)
Diseases named in the same sentence as SIRT3 in open-access papers (continued):
Sharing a sentence is not in itself a finding about the gene and the disease.
tumor (continued). "This phenotype seems to be recapitulated by loss of Sirtuin-3 (Sirt3), a mitochondrial form of lysine deacetylase in tumor cells." (PMID 27023612, 2016). "Together, these results suggest a potential interplay between SIRT3 and a group of glycolysis-associated genes in signaling tumor aggressive growth, which needs to be further investigated." (PMID 26121691, 2015). "Published data revealed that Sirt3 was implicated in tumor progress, mainly through mediating the suppression of hypoxia inducible factor 1α (HIF-1α) and inhibiting mitochondrial ROS production." (PMID 24774224, 2014). "The OSCC_32 patient carried either s.477G > T or c.622G > A as a heterozygous mutation in both normal and tumor tissues, indicating there was a germ-line genetic alteration of the SirT3 gene." (PMID 23800187, 2013). "Our further study indicated that low SIRT3 expression in HCC patients with tumor size (<5 cm), grade (I–II), or stage (I–II) associated with poorer overall survival but not recurrence-free survival." (PMID 23272146, 2012). "Collectively, these data indicated loss of SIRT3 was coincident with tumor progression, which suggests SIRT3 as a tumor suppressor in HCC." (PMID 23272146, 2012). "This upregulation suggests a potential link to tumor aggressiveness, where higher levels of SIRT3 may be associated with an increased survival capacity of tumor cells." (PMID 40710366, 2025). "This reduction in SIRT3 is associated with enhanced tumor growth and poor prognosis." (PMID 41471349, 2025). "Moreover, sustained SIRT3 overexpression has been associated with both tumor‐suppressive and tumor‐promoting effects in different cancers, raising concerns about the long‐term safety of SIRT3 activation." (PMID 41276460, 2025). "Similarly, mitochondrial sirtuins, especially SIRT3, interact with mTOR regulators and inhibit tumour progression, also sensing the nutrient deficiency via NAD+ and activating the AMPK pathway to restore balance." (PMID 40908838, 2025). "NAMPT/SIRT pathway also contributes a lot to NET-associated tumor angiogenesis, in which SIRT3 is capable of regulating endothelial cells, thereby stimulating the ROS generation and modulating the hypoxia-inducible factor, culminating in the preferment of angiogenesis." (PMID 39430756, 2024). "Low-Sirt3 fibroblasts are associated with tumor stroma, and they may play a supporting role in tumor progression." (PMID 39596133, 2024). "The tumor suppressor effects of SIRT3 are primarily associated with metabolism regulation, and the regulation of cancer metabolic reprogramming by SIRT3 is mainly achieved through modulation of tumor cell glycolysis." (PMID 39479446, 2024). "Similarly, Sirt3 deficiency accelerates the acetylation-dependent deactivation of succinate dehydrogenase complex subunit A to increase H3K4me3 level, which leads to tumour-specific gene transcription." (PMID 36739437, 2023). "However, the results of this study showed that autophagy, caused by SIRT3 downregulation promotes it as a tumor suppressor." (PMID 35571098, 2022). "Whether this represents an additional mechanism for SIRT3-mediated SOD2 activation in response to stress associated with tumor progression requires further investigation." (PMID 29099803, 2017). "Increasing evidences have linked SIRT3 in tumor development." (PMID 27367026, 2016). "As alterations of mitophagy and apoptosis have been known to be associated with tumor development, progression, and therapy, our study on the role of Sirt3 in regulating these two cellular processes provides evidence for exploiting Sirt3 as a new target for prevention and treatment of cancer." (PMID 27270321, 2016). "Our data support such a hypothesis whereby low levels of SIRT3 promote proliferation, and are associated with more aggressive tumours that benefit from chemotherapy that targets rapidly proliferating cells." (PMID 26121130, 2015).
tumor (continued). "Interestingly, SIRT3 deficiency is associated with tumor growth in xenografts and SIRT3 expression is lowered in several cancers and cancer cell lines." (PMID 23408731, 2013). "This idea was further validated by the finding that in 5 of 21 OSCC patients, the SIRT3 mutation carried c.622G > A as a heterozygous mutation in both normal and tumor tissues, indicating that these patients had a germ-line genetic alteration of the SIRT3 gene." (PMID 23800187, 2013). "To validate our results and discriminate whether the detected SIRT3 mutations were present in the germ-line cells or somatic cells, we performed targeted exon sequencing of DNA isolated from tumor and normal cells of patients." (PMID 23800187, 2013). "In addition, several recent reports demonstrated the involvement of Sirt3 in diverse cellular processes such as fatty acid metabolism, oxidative stress response, tumor suppression, and age-associated hearing loss." (PMID 23236377, 2012). "All these aspects make Sirt3 a key protein in maintaining cellular stability, and its deficiency or aberrancy lies in the basis of many diseases, including cancers, especially since Sirt3 itself may act as a tumor-suppressor." (PMID 35440893, 2022). "Notably, Sirt3 deficient mice were resistant to the tumor promoting effect of HFD." (PMID 31970087, 2019). "Similarly, our study demonstrated that the transcription levels of SIRT3 in different subtypes of OC were remarkably lower than those in normal samples, and its increased mRNA expression was significantly associated with tumor stage II and favorable outcome in OC." (PMID 31572453, 2019). "Indeed, SIRT4 seems to have a tumor-suppressor role similar to that of SIRT3, as SIRT4-null mice develop lung tumors, loss of SIRT4 accelerates tumor progression in a mouse Burkitt lymphoma model and SIRT4 expression is reduced in several types of human cancers." (PMID 30197878, 2018). "However, it is unclear whether the aberrant expression of SIRT3 in patients with GC is a causal factor, a subsequent effect of tumor progression, or if other mutations play a role in GC." (PMID 27686535, 2017). "SIRT3 was thought to participate a wide range of cancerous functions, including genomic instability and mutation, resisting cell death, sustaining proliferative signaling, deregulating cellular energetics, evading growth suppressors, as well as tumor-promoting inflammation." (PMID 27483432, 2016). "Likewise, low levels of cytoplasmic SIRT3 were associated with high grade tumours (p = 0.035)." (PMID 26121130, 2015). "However, less is currently known about the genetic polymorphism of SIRT3 in tumor cells." (PMID 23800187, 2013). "While SIRT3 has been described as a tumor suppressor in some contexts and as a tumor promoter in others, its role appears to be tissue- and metabolism-specific." (PMID 41683751, 2026). "Sirt3 has been recognized as a tumour suppressor and inhibits tumour growth and carcinogenesis by reducing mtROS production." (PMID 40177131, 2025). "In parallel, SIRT3 enhances OXPHOS efficiency via ETC assembly optimization in neoplasms, unveiling potential therapeutic vulnerabilities in OXPHOS-dependent malignancies such as pancreatic adenocarcinoma and BRAF-mutated melanomas." (PMID 40860195, 2025). "This dual function—tumor inhibition and protection of host tissue—highlights the therapeutic value of SIRT3 activation in chemotherapy." (PMID 41425553, 2025). "Honokiol, a SIRT3 agonist, reduces cyclin E2 lactylation levels and effectively inhibits tumor proliferation." (PMID 40994548, 2025). "Beyond its role in genome stability, SIRT3 exerts metabolic control in a context-dependent manner, predominantly acting as a tumor suppressor." (PMID 40860195, 2025). "Aspirin inhibits tumor growth by activating the AMPK/SIRT3/HK-II pathway, leading to hexokinase 2 (HK-II) dissociation from mitochondria, impaired glycolysis, and mitochondrial dysfunction." (PMID 40710178, 2025).
tumor (continued). "Conversely, for tumors that depend on increased glycolytic activity, SIRT3 functions as a tumor suppressor." (PMID 41304967, 2025). "The results show that intratumoral injection of RSL3 significantly decreased tumor growth and, more interestingly, that inhibition of SIRT3 by 3-TYP further attenuated the growth of the implanted tumors." (PMID 40298644, 2025). "In vivo, fraxinellone inhibits GBM tumor growth through inactivation of the SIRT3 signaling pathway, reinforcing SIRT3’s critical role in GBM tumorigenesis and its potential as a therapeutic target." (PMID 40710366, 2025). "As a mitochondrial deacetylase, SIRT3 serves as a molecular nexus intersection of cellular senescence and oncogenesis, exerting tumor-suppressive effects by preserving genomic integrity through multiple regulatory mechanisms." (PMID 40860195, 2025). "Depending on the cellular context, this regulation can either promote or suppress fission, suggesting that SIRT3 fine-tunes mitochondrial morphology, bioenergetic efficiency, and ultimately tumor cell fate." (PMID 41304967, 2025). "On the other hand, a small molecule activator of SIRT3 inhibited tumor cell proliferation and migration in RKO and HCT-116 cell lines by triggering autophagy-dependent cell death and apoptosis by regulating the SIRT3/Hsp90/AKT signaling pathway." (PMID 40943150, 2025). "Immunohistochemistry staining of the tumor samples confirmed that SIRT3 protein levels were substantially increased in the SIRT3-OE xenografts." (PMID 41391757, 2025). "Future investigations should aim to delineate the disease-specific chromatin landscapes modulated by SIRT3, with a particular focus on its roles in tumor biology, neurodegenerative disorders, and viral pathogenesis." (PMID 40860195, 2025). "Collectively, SIRT3 is a strong tumor suppressor molecule during malignant progression in ESCC cells." (PMID 40252727, 2025). "Overexpression of SIRT3 enhances mitochondrial respiration and reduces ROS production, thereby promoting tumor growth." (PMID 41304967, 2025). "During GSCs’ differentiation into bulk tumor cells, SIRT3 is degraded through the autophagy–lysosome pathway, triggered by glutamine deprivation, which restricts CD133 expression and disrupts GSC stemness." (PMID 40710366, 2025). "To explore how Arg-II promotes mtROS generation, we investigated the effect of a mitochondrial tumour suppressor Sirt3 that has been reported to limit tumour growth by inhibiting mtROS production." (PMID 40177131, 2025). "SIRT3 has emerged as a key regulator of tumor cell metabolism, its role can be either pro-oncogenic or tumor suppressive depending on the cell type." (PMID 41226512, 2025). "Conversely, under certain pathological conditions such as malignancy, SIRT3 exerts pro-apoptotic effects by facilitating mitochondrial apoptotic signaling, thereby impeding tumor proliferation and viability." (PMID 40860195, 2025). "Future research should focus on dissecting the spatiotemporal regulation of SIRT3 activity, as well as identifying interacting molecular co-factors or modifications that determine its tumor-suppressive versus pro-tumorigenic roles." (PMID 40860195, 2025). "SIRT3 also exerts tumor-suppressive effects through activation by PGC-1α, which enhances oxidative phosphorylation while inhibiting glycolysis and cellular proliferation, an activity correlated with improved patient survival." (PMID 41471349, 2025). "Immunohistochemistry staining of these mouse tumor samples confirmed that SIRT3 protein levels were indeed decreased in vivo." (PMID 41391757, 2025). "The role of SIRT3 in cancer development has been reported to include both tumor-suppressive and tumor-promoting functions." (PMID 41154474, 2025). "In colorectal malignancies, SIRT3 optimizes serine metabolism via serine hydroxymethyltransferase 2 deacetylation at Lys95, enhances tumor aggressiveness." (PMID 40860195, 2025).
tumor (continued). "A study utilizing ultrasound-targeted microbubble destruction (UTMD) gene delivery demonstrated that SIRT3 functions as a tumor suppressor in ovarian cancer." (PMID 41471349, 2025). "For instance, SIRT3 catalyzes Lys228 deacetylation on pyrroline-5-carboxylate reductase 1, facilitating proline biosynthesis, a critical process for tumor cell proliferation." (PMID 40860195, 2025). "While SIRT1, SIRT2, and SIRT6 can assume opposite functions in relation to the tumor context, SIRT3, SIRT4, and SIRT7 tend to function more in favor of tumors." (PMID 41425553, 2025). "Intriguingly, the role of SIRT3 in autophagy is context-dependent, with evidence suggesting it can both inhibit tumor progression and protect tumor cells under stress." (PMID 38773972, 2024). "The decreased SIRT3 expression correlated strongly with an advanced T status and tumor stage (p < 0.001 and p = 0.013, respectively), suggesting that SIRT3 downregulation is intricately linked to more aggressive disease manifestations." (PMID 39682281, 2024). "Overall, our paper highlights a new SIRT3 role in regulating the response and survival of tumor cells to acidic pHe by modulating the activity of mitochondrial CAVB." (PMID 38931477, 2024). "In vitro experiments demonstrated that the downregulation of SIRT3 resulted in increased sensitivity of OSCC cells to radiation and cisplatin treatments, causing a significant reduction in tumor burden." (PMID 38702756, 2024). "SIRT3, in particular, is often viewed as a tumor suppressor due to its ability to regulate mitochondrial function and reduce oxidative stress, which can inhibit cancer cell growth." (PMID 39682281, 2024). "In a comprehensive analysis of sirtuin family proteins, SIRT3 exhibited tumor-suppressive characteristics, particularly in PDAC." (PMID 39682281, 2024). "In terms of its tumor-suppressive functions, SIRT3 induces apoptosis by activating key components of the apoptotic machinery." (PMID 38773972, 2024). "Collectively, SIRT3 act as tumor suppressor in PCa by regulating key metabolic and oncogenic pathways, including the inhibition of ACO2 acetylation and suppression of the Wnt/β-catenin signaling pathway." (PMID 39796040, 2024). "We propose SIRT3 plays a tumor suppressor role, which is partly due to promote ROS production in NSCLC cells." (PMID 39501597, 2024). "Research on the role of SIRT3 in tumor cell ferroptosis is only emerging, and the results so far have been inconsistent." (PMID 38395990, 2024). "This underscores a novel mechanistic link between SIRT3’s tumor-suppressive function and its regulation of cellular iron metabolism, positioning SIRT3 as a critical metabolic modulator in pancreatic carcinogenesis." (PMID 39682281, 2024). "SIRT3 has emerged as a pivotal regulator of cancer cell metabolism, oscillating between oncogenic and tumor-suppressive roles." (PMID 38773972, 2024). "This dualistic nature of SIRT3 underscores the intricacies of cancer metabolism and highlights the nuanced interplay between metabolic pathways and tumor progression." (PMID 38773972, 2024). "On the other hand, SIRT3 is described as a tumor suppressor gene in OvCa and its expression increases in detached cells and tumor cells from malignant ascites, indicating its pro-metastatic role in OvCa." (PMID 39349928, 2024). "SIRT3 acts as a tumor suppressor by undermining the Warburg effect through destabilizing HIF1α, a key transcription factor for glycolytic gene expression." (PMID 38773972, 2024). "This regulatory axis underscores the interplay between miR-421 and SIRT3 in manipulating the cellular hypoxic response and glycolytic activity, thereby promoting a more aggressive tumor phenotype." (PMID 39682281, 2024). "On the other hand, downregulation of SIRT3 has also been reported to increase tumor growth and survival." (PMID 38931477, 2024). "SIRT3, a tumor suppressor, regulates mitochondrial metabolism and oxidative stress, counteracting tumor progression." (PMID 39682281, 2024).
tumor (continued). "SIRT3, downregulated in prostate cancer, acts as a tumor suppressor, modulating protein kinase B and Wnt/β-catenin pathways, inhibiting migration and proliferation." (PMID 38331199, 2024). "Pancreatic cancer unveils SIRT3 as a tumor suppressor activating the malate-aspartate shuttle, facilitating increased ATP production, and supporting cancer cell proliferation." (PMID 38331199, 2024). "This modulation of critical metabolic pathways via acetylation and deacetylation exemplifies the nuanced regulatory capacity of SIRT3, positioning it as a central mediator in the metabolic reprogramming of tumor cells." (PMID 38542426, 2024). "SIRT3 also acts as a tumor suppressor in B cells, specifically malignant B cells from patients where SIRT3 expression is reduced compared to healthy patients." (PMID 39157755, 2024). "SIRT3, a pivotal mitochondrial deacetylase, exhibits a dual role in cancer biology, acting as either an oncogene or tumor suppressor depending on the tumor context." (PMID 39682281, 2024). "SIRT2, conversely, disrupts cancer cell proliferation by inhibiting eIF5A, while SIRT3 exerts tumor-suppressive effects by regulating mitochondrial ROS and glycolysis." (PMID 39682281, 2024). "SIRT3's dualistic nature, acting as both a tumor suppressor and an oncogene depending on the cancer context, highlights the critical importance of targeted therapy." (PMID 38773972, 2024). "As a major mitochondrial NAD+-dependent deacetylase, SIRT3 target diverse substrate proteins to perform various functions including regulation of oxidative stress, reprogramming of tumor cell energy pathways, and metabolic homeostasis." (PMID 38470932, 2024). "Overall, our findings suggested that SIRT3 functions as a tumor suppressor that can suppress the progression of NSCLC via stimulating ROS production." (PMID 39501597, 2024). "Decreased SIRT3 expression correlates with higher Gleason scores and metastatic potential, suggesting that SIRT3 acts as a tumor suppressor by restraining cell migration and invasion." (PMID 39796040, 2024). "On the other hand, SIRT3 generally functions as a tumor suppressor, primarily by regulating mitochondrial function and oxidative stress." (PMID 38794205, 2024). "For example, SIRT3 can promote tumor growth by enhancing the deacetylation and thus activity of SHMT2, but it can also exert anti-tumor effects by increasing SOD2 activity and reducing ROS production." (PMID 39763669, 2024). "Its ability to modulate autophagy and mitigate mitochondrial ROS generation, particularly via the SIRT1- and SIRT3-mediated pathways, highlights its potential utility in disrupting tumor growth." (PMID 39682281, 2024). "Our results point to the possibility of modulating SIRT3 to decrease the response and resistance of tumor cells to the acidic microenvironment and ameliorate the effectiveness of anticancer therapy." (PMID 38931477, 2024). "This phenomenon underscores SIRT3’s dual role as a tumor promoter or suppressor, contingent on the cancer context, with implications in various cancer types." (PMID 38542426, 2024). "SIRT3, a mitochondrial deacetylase, plays a context-dependent role in cancer as both a tumor suppressor and an oncogene, influenced by the specific circumstances." (PMID 38773972, 2024). "In contrast, tumor-suppressive Sirtuins like SIRT3 and SIRT4 counteract these processes by reprogramming hypoxia-driven oncogenic pathways." (PMID 39682281, 2024). "As a key regulator of tumor metabolism, SIRT3 participates in the metabolic reprogramming of mitochondria and can regulate the level of ROS to play a role in tumor inhibition, which is a significant feature of SIRT3." (PMID 38773972, 2024). "Functionally, miRNA-708-5p directly targets and suppresses SIRT3 expression, thereby disrupting its tumor-suppressive role." (PMID 39682281, 2024). "In cholangiocarcinoma, SIRT3 plays a tumor-suppressive role by downregulating the HIF1α/PDK1/PDHA1 pathway, leading to tumor regression." (PMID 39620228, 2024).